CCDC26 (CCDC26 long non-coding RNA)
Synonyms: MGC27434; RAM; LINC00977; GLM7; LINC00976
Gene: Long non-coding RNA gene on chromosome 8 (128,634,199 to 129,723,023, reverse strand). Ensembl gene ENSG00000229140.
Diseases named in the same sentence as CCDC26 in open-access papers:
CCDC26 is named in the same sentence as 34 diseases in open-access papers, as found by Europe PMC text mining. Sharing a sentence is not in itself a finding about the gene and the disease. The quoted sentences say what the papers report.
glioma (33 papers, 2011 to 2025). A benign or malignant brain and spinal cord tumor that arises from glial cells (astrocytes, oligodendrocytes, ependymal cells). "The CCDC26 germline variant rs55705857 is causal for development of IDH mutant (IDHmut) adult glioma." (PMID 40709013, 2025). "While it is already known that the CCDC26 is a causal variant for IDHmut glioma, these findings highlight the importance of prioritizing the PHLDB1 and D2HGDH regions in future functional experiments." (PMID 40709013, 2025). "The known glioma risk variant rs55705857 in CCDC26 was co-inherited together with rare variants in GALNT13, MYO10 or AR in three out of six families carrying these rare variants, and it was also detected in affected cases in three additional families." (PMID 38773237, 2024). "In particular, CCDC26, which we considered a low-risk lncRNA for glioma survival and expressed higher in the low-risk group, has been identified as having the function of inhibiting the growth and migration of glioma cells." (PMID 37152037, 2023). "For example, high-grade gliomas are associated with risk variants in RTEL1, CDKN2B, and TERT, while low-grade gliomas with IDH mutation-1p/19q codeletion are associated with risk variants in CCDC26 and PHLDB1 regions." (PMID 31968687, 2020). "The nature of CCDC26 remains ambiguous but it is more plausible that the CCDC26 locus encodes a long non-coding-RNA involved in tumors, including low-grade gliomas and pancreatic cancer." (PMID 29464086, 2018). "Additionally, structural variations in CCDC26 have been linked to pediatric gliomas, such as diffuse intrinsic pontine glioma (DIPG), where they contribute to elevated gene expression and tumor proliferation." (PMID 41003104, 2025). "CCDC26 rs4295627 polymorphism was a risk marker for glioma patients." (PMID 38431660, 2024). "When considering the rate, inheritance pattern, and population frequencies of detected rare, damaging coding variants in MYO10, AR and GALNT13, enhancer-linked risk variant in CCDC26, and other detected risk variants, our results suggest polygenic inheritance of familial glioma in Finland." (PMID 38773237, 2024). "In addition, affected cases in six families carried a known glioma risk variant rs55705857 in CCDC26 and low-risk glioma variants." (PMID 38773237, 2024). "Finally, in glioma, the rs55705857 SNP in the intronic region of the CCDC26 gene adjacent to MYC is not only associated with IDH-mutated gliomas but also appears to confer enhanced MYC activity, potentially affecting its transactivation ability." (PMID 37443779, 2023). "The CCDC26 gene, located on chromosome 8q24, has emerged as a significant player in various cancers, particularly gliomas and acute myeloid leukemia (AML)." (PMID 41003104, 2025). "Silencing of CCDC26 can strongly reduce the wound closing rate and the number of invasive cells and further regulates the growth and metastasis of gliomas." (PMID 36045445, 2022). "Third, variants in CCDC26 (the 8q24 locus), C2orf80 (close to IDH), LRIG1, PHLDB1, ETFA, MAML2 and ZBTB16 were associated with IDH-mutant glioma." (PMID 31842352, 2019). "CCDC26 is upregulated in glioma and promotes the growth and metastasis of glioma by targeting miR-203." (PMID 29552296, 2018). "Variants in CDKN2B and RTEL1 are strongly associated with high-grade glioma while variants in CCDC26 and PHLDB1 are associated with low-grade glioma." (PMID 26839018, 2016).
glioma (continued). "Variants of the CCDC26 and PHLDB1 genes have predominantly been associated with low grade glioma, and there is a clear correlation between these variants and IDH1 mutation status." (PMID 23236348, 2012). "According to data analysis results, in four genetic models (AM, RM, DM and C-DM) TERT gene rs2736100 polymorphism, CCDC26 gene rs4295627 polymorphism, CDKN2A/B gene rs4977756 polymorphism and RTEL1 gene rs6010620 polymorphisms increased the risk of glioma in Caucasians to different degrees." (PMID 37746290, 2023). "A case-control study recruited 855 high-grade glioma patients from four different geographic regions of the US and belonging to five inherited glioma risk variants: 5p15.3 (TERT), 8q24.21 (CCDC26/MLZE), 9p21.3 (CDKN2B), 11q23.3 (PHLDB1/DDX6) and 20q13.3 (RTEL1)." (PMID 30909395, 2019). "In Asian populations, the CCDC26 gene rs4295627 polymorphism and CDKN2A/B gene rs4977756 polymorphism did not exhibit a relevance to the risk of glioma." (PMID 37746290, 2023). "In glioma, genome-wide association studies have identified common genetic variations in 7 genes that increase glioma risk (TERT, EGFR, CCDC26, CDKN2A, CDKN2B, PHLDB1 and RTEL1) but BRCA1 is not among them and there is no known association between BRCA1 gene and glioblastoma multiforme (GBM)." (PMID 25880076, 2015). "However, CCDC26 has never been reported to be expressed in gliomas." (PMID 27282637, 2016).
myeloid leukemia (8 papers, 2015 to 2024). A clonal proliferation of myeloid cells and their precursors in the bone marrow, peripheral blood, and spleen. "For example, lncRNA CCDC26 was found to be a novel biomarker in acute myeloid leukemia and also found to control myeloid leukemia cell growth." (PMID 34464437, 2021). "Several studies have demonstrated that CCDC26 controls myeloid leukemia cell growth through regulating KIT expression." (PMID 31619233, 2019). "While CCDC26 controls myeloid leukemia cell growth, GCS1684 is specifically expressed in spleen, a major storage location for leukocytes and shows significant allelic imbalance in 8/13 melanoma samples (FDR < 0.05)." (PMID 29284497, 2017). "We found that CCDC26 transcripts were abundant in the nuclear fraction of K562 human myeloid leukemia cells." (PMID 25928165, 2015). "We suggest that CCDC26 controls growth of myeloid leukemia cells through regulation of KIT expression." (PMID 25928165, 2015). "Interestingly, it has been recently suggested that CCDC26 could control myeloid leukemia cell growth through regulation of KIT expression." (PMID 29464086, 2018). "In line with previous reports, we identified reduced transcription of Myc after I-BRD9 treatment, as well as the neighboring long noncoding RNA (lncRNA) Ccdc26, transcription of which is suppressed during differentiation of HL60 myeloid leukemia cells." (PMID 38126767, 2024). "In the absence of CCDC26, DNMT1 is mis-localized in the cytoplasm, leading to DNA hypomethylation and apoptosis similar to that observed on inhibition of DNMT1 in myeloid leukemia cells." (PMID 33851096, 2021).
acute myeloid leukemia (7 papers, 2015 to 2025). Acute myeloid leukemia (AML) is a group of neoplasms arising from precursor cells committed to the myeloid cell-line differentiation. "It is of specific interest in acute myeloid leukemia (AML) because of the high-frequency occurrence of AML-associated mutations and variants in CCDC26 gene." (PMID 33851096, 2021). "The lncRNA, CCDC26, is related to childhood acute myeloid leukemia (AML) because its copy number is altered in AML patients." (PMID 25928165, 2015). "Lnc-CCDC26, lnc-DARS-AS1 and lnc-SNHG14 play oncogenic roles in childhood acute myeloid leukemia (AML)." (PMID 34112247, 2021). "CCDC26, a long noncoding RNA located within the ~2 Mb MYC locus and frequently amplified in leukemia, has been shown to regulate acute myeloid leukemia cell proliferation through KIT signaling and to influence erythroid differentiation via FOG-2–mediated transcriptional control of globin genes." (PMID 41509392, 2025).
leukemia (7 papers, 2015 to 2025). A malignant (clonal) hematologic disorder, involving hematopoietic stem cells and characterized by the presence of primitive or atypical myeloid or lymphoid cells in the bone marrow and the blood. "Disruptions in CCDC26 have been linked to leukemia and pancreatic cancer, with elevated expression associated with poor prognosis." (PMID 40563675, 2025). "Finally, CCDC26 disruption was found in both subtypes (4.5% of the whole cohort) and possibly highlighted a new lesion associated with aberrant tyrosine kinase signaling in this particular subtype of leukemia." (PMID 29464086, 2018). "This connection between CCDC26 and DNMT1 can provide the missing link between frequent mutations in CCDC26 locus and leukemia." (PMID 33851096, 2021). "A new study on leukemia showed that CCDC26 is highly expressed in AML cells HL-60 and CML cells K562." (PMID 34113488, 2021). "We further examined this by measuring CCDC26 levels in a number of additional leukemia and non-leukemia lines." (PMID 33851096, 2021). "Thus, considering the high frequency class I mutations (especially in KIT, FLT3 and RAS genes) in CBF-AML, it is likely that CCDC26 disruption could highlight a new class I aberration leading to increased cell survival and proliferation in leukemia." (PMID 29464086, 2018). "Although CCDC26 is a low-burden amplified gene expressed in some leukemia cells, amplification occurs partially and does not extend across the whole gene in most cases." (PMID 25928165, 2015). "CCDC26, a long non-coding RNA gene, and CD38, a gene associated with activation and multiple myeloma, were suppressed, indicating that these cells were differentiated and no longer displaying the leukemia phenotype." (PMID 36982186, 2023).
pancreatic cancer (7 papers, 2018 to 2025). "Previous studies have shown that lncRNA CCDC26 levels were correlated with tumor size, tumor number, and reduced overall survival in pancreatic cancer." (PMID 36045445, 2022). "CCDC26, as a potential predictor biomarker, contributes to tumorigenesis in pancreatic cancer." (PMID 31619233, 2019). "Additionally, a study on pancreatic cancer and CDC26 showed that CCDC26 was responsible for the growth and apoptosis of pancreatic cancer cells, partly by regulating PCNA and Bcl2 expression." (PMID 31619233, 2019).
glioblastoma (5 papers, 2014 to 2025). The most malignant astrocytic tumor (WHO grade IV). "A single nucleotide polymorphism (SNP) rs891835 in CCDC26 is reportedly associated with glioblastoma susceptibility." (PMID 26305674, 2015). "The lncRNA coiled-coil domain-containing 26 (CCDC26) was identified as a retinoic acid-dependent modulator and plays an important role in the pathogenesis of glioblastoma." (PMID 38414063, 2024).
thyroid cancer (3 papers, 2022 to 2024). "CCDC26 can regulate miRNA through multiple pathways in thyroid cancer to promote the cancer occurrence." (PMID 39877345, 2024). "CCDC26 promotes thyroid cancer malignant progression via miR-422a/EZH2/Sirt6 axis." (PMID 36045445, 2022).
gastrointestinal stromal tumor (2 papers, 2019 to 2022). "CCDC26 can affect the drug sensitivity in gastrointestinal stromal tumors and the prognosis." (PMID 36045445, 2022).
lumbar disc degeneration (2 papers, 2018 to 2023). "For instance, the genes found in chronic back pain are involved in chondrogenesis (SOX5 and SOX673) or lumbar disc degeneration (CCDC26/GSDMC8)." (PMID 37144689, 2023).
lung carcinoma (2 papers, 2023 to 2025). "In dataset 1, LDAenDL predicted that CCDC26 could be associated with lung cancer." (PMID 37655066, 2023). "The results demonstrated that CCDC26 and IFNG-AS1 may be new biomarkers for lung cancer, SNHG3 may be associated with PDL1 for lung cancer, and HOTAIR and BDNF-AS may be potential biomarkers for neuroblastoma." (PMID 37655066, 2023). "Case studies demonstrate that CCDC26 and IFNG-AS1 may be new biomarkers of lung cancer, SNHG3 may associate with PDL1 for lung cancer, and HOTAIR and BDNF-AS may be potential biomarkers of neuroblastoma." (PMID 37655066, 2023). "Furthermore, AI has shown that new biomarkers, such as CCDC26 and interferon gamma antisense RNA 1 (IFNG-AS1), may be related to lung cancer and Small Nucleolar RNA Host Gene 3 (SNHG3) may be associated with PD-L1." (PMID 40075729, 2025).
mammary tumors (1 paper, 2016). "In a recent study, chromosomal engineering in mice showed that copy number gains in the Myc gene promote tumorigenesis in mammary tumors only if the downstream sequence encompassing Pvt1, Ccdc26, and Gsdmc is also amplified, suggesting that GSDMC may play a role in tumor progression." (PMID 27835699, 2016).
plasma cell tumor (1 paper, 2019). "In this study, the differential expression of CCDC26 was identified, providing a novel biomarker and therapeutic target of plasma cell tumor for MM therapy in the future." (PMID 31619233, 2019).
radiculopathy (1 paper, 2021). Disease involving a spinal nerve root (see spinal nerve roots) which may result from compression related to intervertebral disk displacement; spinal cord injuries; spinal diseases; and other conditions. "Thus, we aimed to examine if LBP with radiculopathy 12 months after an acute episode of radiculopathy is associated with the selected SNPs; SOX5 rs34616559, CCDC26/GSDMC rs7833174 and DCC rs4384683." (PMID 35140737, 2021). "Thus, we examine if LBP with radiculopathy 12 months after an acute episode of LBP with radiculopathy is associated with the selected single nucleotide polymorphisms (SNPs); SOX5 rs34616559, CCDC26/GSDMC rs7833174 and DCC rs4384683." (PMID 35140737, 2021). "Our data did not support the hypothesis that LBP with radiculopathy 12 months after an acute episode of LBP with radiculopathy is associated with the selected SNPs; SOX5 rs34616559, CCDC26/GSDMC rs7833174 and DCC rs4384683." (PMID 35140737, 2021).
Sciatica (1 paper, 2018). Pain in the lower back and hip radiating in the distribution of the sciatic nerve. "All variants in CCDC26/GSDMC that were suggestively associated with CBP showed cross-phenotypic associations with lumbar microdiscectomy for sciatica in a recent GWAS of Icelandic adults (lowest p = 5.6×10−12)." (PMID 30261039, 2018).
cancer (21 papers, 2015 to 2025). A tumor composed of atypical neoplastic, often pleomorphic cells that invade other tissues. "CCDC26 is a nuclear lincRNA that is frequently mutated in cancers and is a hotbed for disease-associated single nucleotide changes." (PMID 33851096, 2021). "Contrastingly, several of the lincRNAs in this region appear to be hotspots for SNPs including PCAT1 and CCDC26 which are associated with 73 and 81 SNPs, respectively, with many of these SNPs associated with various cancers." (PMID 33499210, 2021). "Within the 8q24.21 region, a large number of cancer-associated SNPs are clustered within the first intron of CCDC26 gene." (PMID 33499210, 2021). "Besides, scholars also found the polymorphism of CCDC26 related to cancer risk." (PMID 36045445, 2022). "On the background that the main transcriptional start site of CCDC26 is located within exon 2 of the gene, we can speculate that cancer-associated SNP hotspot in the first intron may affect the promoter region of CCDC26 and therefore impact expression of the lincRNA." (PMID 33499210, 2021). "In our study, CCDC26 was predominantly hypermethylated within intronic regions, supporting a role for gene body methylation in cancer-related gene regulation." (PMID 40563675, 2025). "At present, the role of Coiled-coil domain containing (CCDC26) in cancer prognosis remains unexplored." (PMID 38431660, 2024). "CCDC26 participates in cancer cell growth and apoptosis by regulating the expression of PCNA and Bcl2." (PMID 36045445, 2022). "LncRNA CCDC26 (CCDC26), located on chromosome 8q24, has been reported to have a tumorigenic role of in many malignant tumors." (PMID 35565245, 2022). "In summary, even though detailed molecular mechanism behind CCDC26-mediated DNMT1 localization still remains to be investigated, our study provides an insight into the role of CCDC26 in cancer as well as a novel lincRNA mechanism of DNMT1 regulation." (PMID 33851096, 2021). "Along with MYC and PVT1, the CCDC26 lncRNA gene lies in the human chromosome 8q21 region that is frequently amplified in cancer." (PMID 31338324, 2019). "In pancreatic cancer, CCDC26 was labeled as a novel oncogene and is responsible for the growth and apoptosis of cancer cells by regulating PCNA and Bcl2 expression." (PMID 31166382, 2019). "Gain of single supernumerary segment encompassing Myc, Pvt1, Ccdc26 and Gsdmc has shown to promote cancer." (PMID 25885205, 2015). "In this study, we aimed to understand the function of CCDC26 and its role in cancer." (PMID 33851096, 2021). "Very few reports characterize the function of CCDC26 in other cancers." (PMID 31166382, 2019). "At the MYC locus (chr8:127–130 Mb), which is subject to cell type–specific enhancer regulation across cancers, H3K27ac HiChIP revealed extensive E-P interactions in control cells linking MYC to PVT1 and CCDC26." (PMID 41509392, 2025). "Several lncRNAs identified in other malignant tumors, such as HOTAIR, CCDC26, and AOC4P, have also been evaluated in GISTs and were shown to be associated with GIST metastasis and sensitivity to imatinib." (PMID 34218261, 2021). "Despite being expressed at roughly one copy per cell in myeloid leukemia cell lines, it is upregulated in these cells compared to other cancer types—including lymphoid malignancies—in which CCDC26 expression is not detectable." (PMID 31338324, 2019).
tumor (14 papers, 2016 to 2025). "We observed that there were statistically significant interactions between IDH tumor mutation status and CCDC26 (rs55705857), PHLDB1 (rs7125115), and D2HGDH (rs71430382) germline variants." (PMID 40709013, 2025). "CCDC26 knockdown could cause imatinib resistance in gastrointestinal stromal tumor cells through decreasing c-KIT expression." (PMID 38431660, 2024). "It is unknown whether this partial amplification of the gene results in a gain or loss of function, but it is likely abnormalities in CCDC26 structure drive a pro-tumour phenotype." (PMID 33499210, 2021). "CCDC26 is highly expressed in PC tissues compared with normal tissues, and its expression is correlated with tumor size, tumor number, and reduced OS." (PMID 35565245, 2022). "In the study, gain of MYC or the PVT1/CCDC26/GSDMC region alone did not result in tumourigenesis, but co-amplification of MYC and PVT1/CCDC26/GSDMC resulted in a pro-tumour transformation." (PMID 33499210, 2021). "Studies have identified complementary base pair regions between the majority of the lincRNAs located in 8q24.21 (PVT1, CCAT1, PCAT1, CCAT2, CASC11, PRNCR1, CASC19, CCDC26) and miRNAs which have been previously identified as tumour suppressors." (PMID 33499210, 2021). "Notably, in contrast to RhOME2, RhOME1 (PCAT1) and RhOME3 (CCDC26) were previously identified as MYC regulatory regions in other tumor entities." (PMID 38040699, 2023). "Knocking down either Myc or PVT1 decreases proliferation of Myc/PVT1/Ccdc26/Gsdmc mutant tumor cells to the same extent as knocking down both PVT1 and Myc, thus suggesting the presence of a common oncogenic pathway shared by Myc and PVT1 in tumor initiation." (PMID 31497532, 2019).